HINT2 (histidine triad nucleotide binding protein 2)
Diseases named in the same sentence as HINT2 in open-access papers (continued):
Sharing a sentence is not in itself a finding about the gene and the disease.
cancer (4 papers, 2016 to 2023). A tumor composed of atypical neoplastic, often pleomorphic cells that invade other tissues. "HINT2 therefore sensitizes cells to apoptosis by altering the expression of MCU regulators, while cancer cells suppress this by downregulating HINT2 expression." (PMID 32059571, 2020). "HINT2 overexpression induces an anti-EMT gene expression profile in cancer cells, inhibiting cell migration, invasion, and metastasis; induces cell apoptosis; decreases mitochondrial membrane potential; promotes intracellular ROS production; and elevates mitochondrial Ca2+ levels." (PMID 37834160, 2023).
infection (2 papers, 2020 to 2025). The state of being infected such as from the introduction of a foreign agent such as serum, vaccine, antigenic substance or organism. "We knocked down SIRT3 by infection with lentivirus-shSIRT3 and found that the reduction in SIRT3 expression significantly aggravated FFA-induced lipid accumulation but abolished the ameliorative effects of HINT2 overexpression in HepG2 cells." (PMID 40307568, 2025).
cardiovascular diseases (1 paper, 2025). "Studies suggest that HINT2 mitigates pressure‐overload‐induced cardiac remodeling by affecting the activity and assembly of mitochondrial complex I. However, research on HINT3, a family member of HINT1 and HINT2, is scarce, especially in the context of cardiovascular diseases." (PMID 40755357, 2025).
metabolic disease (1 paper, 2025). A congenital disorder (due to inherited enzyme abnormality) or acquired (due to failure of a metabolically important organ) disorder resulting from an abnormal metabolic process. "HINT2 has been reported to regulate lipid and glucose metabolism and is considered a promising therapeutic target for metabolic diseases." (PMID 39968501, 2025).
HINT2 also shares sentences with these, for which no sentence is quoted: pancreatic cancer (2 papers); breast carcinoma (1); chronic lymphocytic leukemia (1); colon cancer (1); conjunctival melanoma (1); endometrial cancer (1); Hepatic fibrosis (1); liver disease (1); Myocardial necrosis (1); neuroblastoma (1); Parkinson disease (1).